IL18 (interleukin 18)
Diseases named in the same sentence as IL18 in open-access papers (continued):
Sharing a sentence is not in itself a finding about the gene and the disease.
viral infection (continued). "Among CD56+ cells, 10% are CD56bright cells, which are known for having critical importance in contributing to cytokine production in viral infections, specifically through the production of IL-1, IL-2, and IL-18." (PMID 30944834, 2019). "VSV and HSV-1 induced expression of mRNA transcripts of cytokines, such as Il1b, Il18, Il6, and Il12, were largely comparable between WT and Park2−/− cells after viral infection." (PMID 31229895, 2019). "For all viral infections studied, both Type I IFNs and IL-18 were critical for the activation of these cell populations, thus highlighting the biologic relevance of this cytokine-mediated activation pathway." (PMID 29740432, 2018). "This affects the associated inflammasome complex, which is involved in the control of viral infections and normally plays a role in stimulating an immune response through the production of interleukin-1β (IL-1β) and interleukin-18 (IL-18)." (PMID 29649101, 2018). "IL-12 and IL-18 secreted during viral infections by e.g., dendritic cells induce potent NK cell IFN-γ production and cytotoxicity, in particular in combination, and synergistically augment IL-2 and IL-15–induced NK cell activation." (PMID 30546366, 2018). "DDX58 (RIG-1), OAS, IL-1, IL-12 and IL-18 can augment the immune response and have antiviral effects by sensing viral infection, degrading viral mRNA during viral replication or increasing NK cytotoxicity." (PMID 29073194, 2017). "Upon most viral infections, cDCs produce IL-12, IL-15, and IL-18 (22, –, 24), whereas pDCs rapidly produce large amounts of type I IFNs and also IL-12 (25, –, 27)." (PMID 28904191, 2017). "Upon viral infection, IL-18 release induces a marked elevation of circulation ferritin, explaining the frequently observed hyperferritinemia in viral infections." (PMID 27977798, 2016). "The human immunodeficiency virus (HIV) disease is another viral infection that has been characterized by increased circulating levels of both IL-18 and ferritin." (PMID 27977798, 2016). "Previous research demonstrated that IL-18 and IL-1β are produced upon inflammasome activation in response to some acute viral infections." (PMID 24788318, 2014). "Future studies to investigate the role of CD161++CD8+ T-cell activation by IL-12 and IL-18 in context of viral infections, such as with hepatitis C virus, would be of particular interest." (PMID 24019201, 2014). "Caspase-1 activation and IL-18 and IL-1β maturation are triggered by the assembly of these inflammasome protein complexes in response to some acute viral infections." (PMID 24788318, 2014). "Although we show significant extracellular active IL-1β and IL-18, we also clearly demonstrate the presence of extracellular pro-IL-1β and pro-IL-18 after viral infection of cells." (PMID 23723976, 2013). "Interleukin-1alpha (IL-1α), interleukin-1beta (IL-1β) and interleukin-18 (IL-18) have critical roles in the establishment of neutrophilic inflammation, which is commonly seen in airways viral infection and thought to be detrimental in respiratory disease." (PMID 23723976, 2013). "After viral infection, the amount of IL1α, IL-1β and IL-18 present in the cell medium was measured by ELISA." (PMID 23723976, 2013). "Among the pro-inflammatory mediators, a significant increase in mRNA for CSF2, CSF3, CXCL2, CXCL5, IL6, IL8, and also IL1 and IL18 was observed 24 h after viral infection." (PMID 23723976, 2013). "Consistent with classical activation of the inflammasome by viral infection, significant levels of both IL-1β and IL-18 in their mature forms were detected in the supernatant of infected cells, and caspase-1 inhibition had an impact on this release." (PMID 23723976, 2013). "Infection with this virus was associated with increased expression of IFN-γ and IL-10 in the liver and decreased expression of IFN-γ and IL-18 in the spleen, providing useful information about important mediators involved in immunity against virus infection." (PMID 24204888, 2013).
viral infection (continued). "In viral infections it seems favourable to reduce IL-18BP expression and thereby to enhance antiviral IL-18 activity." (PMID 22761702, 2012). "Several studies have demonstrated the IFN-γ-inductive role played by IL-12 and IL-18 during experimental models of viral infections." (PMID 22206036, 2011). "In THP-1 cells, vMyxM013-KO virus infection can co-ordinantly induce inflammasome-mediated secretion of IL-1β, and IL-18, as well as NF-κB -mediated secretion of various other pro-inflammatory cytokines and chemokines." (PMID 19851467, 2009). "The resulting network revealed a highly interconnected core centered around key cytokines—including IL-6, IL-1β, IL-10, TNF-α, IL-18, and GM-CSF—which function as pivotal hubs driving the host inflammatory response and immunopathogenesis in both viral infections." (PMID 41366310, 2025). "As a rule, an increase in the level of IL-18 in plasma is observed during viral infections." (PMID 39273479, 2024). "During viral infections, IL-18 promotes T-cell activation, which is vital for HCV clearance." (PMID 37978401, 2023). "IL-18 is involved in the lymphocyte response to the disease and it is well established its important role in the complex developing of the host response to viral infection." (PMID 36385417, 2023). "The analysis confirms the previously data concerning the important involvement of IL-6 in the inflammatory response to a virus infection but give also new insights on the mechanisms governing the IL-18 production and regulation in the case of human Sars-CoV2 infection." (PMID 36385417, 2023). "Environmental triggers such as viral infection or danger signals are recognized by monocytes, resulting in the activation of inflammatory pathways and over-production of cytokines, including IL-1β, IL-6, IL-18, and TNF." (PMID 38124139, 2023). "However, it has become clear that MAIT cells also function as rapid sensors of viral infections, where they respond to type I interferons, IL-18 and other components of the initial innate response to infection." (PMID 35562666, 2022). "Activation of NLRP3 or other NLR inflammasomes leading to IL-1β/IL-18 secretion and pyroptosis may also have different impact on viral infection and host cell status in different tissues and organs." (PMID 35173184, 2022). "In addition, MyD88 mediates IL-1 and IL-18 signaling downstream of the IL-1 receptor and inflammasome signaling plays a role in early containment of the viral infection." (PMID 35464475, 2022). "Additionally, MAIT cells are activated by viruses indirectly, through the release of IL-12 and/or IL-18 by innate immune cells during a viral infection." (PMID 35979352, 2022). "Furthermore, memory-like properties of NK cells, with elevated cytotoxicity, can be obtained upon repeated exposure to either viral infections in vivo or combined pre-activation of IL-12, IL-15, and IL-18 cytokines ex vivo." (PMID 33920906, 2021). "The phenotypes presented in pre-activated hypoxic NK cells are quite similar to those recently described for adaptive/memory NK cells, showing enhanced recall responses following either a viral infection or combined IL-12, IL-15, and IL-18 cytokine stimulations." (PMID 33920906, 2021). "Inflammasome activation mediates the conversion of inactive precursor proteins pro-interleukin (IL)-1β and pro-IL-18 into the bioactive forms IL-1β and IL-18, which play important roles in host defense against a variety of bacterial, fungal, and viral infections." (PMID 34356829, 2021). "Together, our data demonstrates that sustained type I IFN signaling is a key determinant of pathogenic neutrophil responses during viral infection, and identifies neutrophil- and type I IFN-dependent IL-18 production as a novel driver of inflammation during genital HSV-2 infection." (PMID 34047696, 2021). "Previous studies have revealed that IL-18 could directly inhibit viral replication in vitro and protect mice from bacterial and viral infection." (PMID 33679805, 2021).
viral infection (continued). "The inflammasome complexes induce the maturation of IL-1β and IL-18, which are important in the defense against viral infections because of their ability to regulate leucocyte migration to the infected area as well as to stimulate the activation and polarization of T cells." (PMID 34946051, 2021). "Furthermore, we observed elevated levels of CXCL8 and CCL2 that promote the recruitment of non-adaptive immune cells to the liver such as monocytes, the main source of IL-15 and IL-18 during viral infections." (PMID 33617602, 2021). "However, MAIT cells also function as innate sensors of inflammation and viral infection via activation by cytokines such as IL-18 and IFN-α." (PMID 32989174, 2020). "ELISA analysis showed that IL-1β and IL-18 secretion was markedly augmented in Park2−/− cells relative to WT counterparts after viral infection, whereas the production of tumor necrosis factor (TNF)-α, an inflammasome-independent cytokine, was not affected by Park2 deletion." (PMID 31229895, 2019). "In addition to the potent induction of IFN-γ, IL-18 activates CD8+ T cells, which play a central role in viral clearance, suggesting a role for IL-18 in viral infection." (PMID 30717382, 2019). "Contrary to the results obtained in this study, in the different viral infections caused by the following oncogenic viruses - Epstein Barr Virus (EBV), Hepatitis B Virus (HBV) and Hepatitis C Virus (HCV), - there was an increase in expression of IL-18." (PMID 31554368, 2019). "Furthermore, a prior report suggested that viral infection activated MAIT cells indirectly via IL-18 synergistically with type I IFN signals." (PMID 31611259, 2019). "The increase in lymphoid aggregates and concomitant increase in IL-18 may therefore be a physiological response to increased bacterial colonisation and bacterial and viral infection frequency in the vulnerable lungs of severe COPD patients." (PMID 28830544, 2017). "Our results suggest that NK cell activity may be therapeutically enhanced by administering IL-15 and IL-18 in virus infections that inadequately activate NK cells." (PMID 28904191, 2017). "This cytokine mode of activation may be a useful tool for the immune system in the context of viral infection where IL-12 and IL-18 are induced, and MAIT cell production of IFNγ in the local milieu can have direct antiviral effects." (PMID 28742082, 2017). "Besides an increased NK cell accumulation, we observed a higher maturation state of mucosal NK cells in presence of IL-18, which is in line with previous findings addressing IL-18 function during NK cell responses upon viral infections." (PMID 27341123, 2016). "Thus, the IL-18 response in viral infections is responsible for hyperferritinemia, while bacterial infections are characterized by an IL-1β/IL-6 response, culminating in elevated plasma levels of CRP." (PMID 27977798, 2016). "Moreover, IL-18 plays a critical role in the host defense against viral infection, promoting cell-mediated immunity via activation of NK and Th1-type cells." (PMID 27682100, 2015). "Therefore, the present data for the first time provide valuable insight into the use of combined administration of type I IFN and IL-18 in controlling viral infection in the poultry industry." (PMID 22776696, 2012). "Moreover, while the ability of pDC to potently stimulate NK cells has been proposed to result from the high levels of IFN-α/β and IL-12 secreted following viral infection, we define a role for IL-18 in this process." (PMID 17407097, 2007). "The ability of MAIT cells to be activated by cytokines allows MAIT cells to respond to a variety of infections, including viral infections, where cytokines such as IL-18 and IL-12 may be released from activated antigen-presenting cells or virally infected cells." (PMID 40135871, 2025).
viral infection (continued). "Furthermore, our work is consistent with reports showing that IL-18-stimulated NK cells target the epithelium during viral infection, delaying reepithelization, and that NK cells also target hematopoietic stem cells that upregulate NKG2D ligands in response to genotoxic stress." (PMID 40935830, 2025). "Upon IAV infection in vivo, MAIT cell recruitment was impaired by IL-18 deficiency, while their activation was affected by deficiency of IL-15, IL-18, IFNαR and most dramatically of IL-12; indicating the involvement of various cytokines in coordinating MAIT cell responses to viral infections." (PMID 40519914, 2025). "Studies on pharmacological inhibition of various viral diseases have shown that inhibition of Caspase-1 could block the GSDMD-mediated cell pyroptosis process and reduce the expression levels of IL-1β and IL-18, leading to corresponding therapeutic effects on viral diseases." (PMID 38132483, 2023). "Upon infection, various cardiac-resident cells, such as cardiomyocytes, endothelial cells, mast cells, phagocytes, and fibroblasts, secrete cytokines IL-1β, and IL-18, contributing to acute inflammation, and treatment with IL-1β could break the resistance of C57Bl/6 (H‐2b) mice to viral infection." (PMID 35997820, 2022). "An upregulation of miR-197 by hepatitis B virus (HBV) significantly repressed IL-18 expression in the THP-1 cell line and positively correlated with the severity of HBV-associated liver disease symptoms, indicating towards a key role of IL-18 in modulating immune response against viral infections." (PMID 33918087, 2021). "NK cells are activated after vaccination against pathogens including influenza, yellow fever and tuberculosis, and their subsequent maturation, proliferation and effector function is dependent on myeloid accessory cell‐derived cytokines such as IL‐12, IL‐18 and type I interferons." (PMID 29484187, 2018). "Hence, a coordinated availability of IL-12, IL-15, and IL-18, derived from dendritic cells and myeloid cells during viral infections such as CMV or influenza, might support generation of cytokine-induced memory-like NK cells in vivo." (PMID 30546366, 2018). "Furthermore, the elevated serum IFN-γ and IL-18 levels observed in these patients might also reflect a systemic inflammatory reaction against an acute viral infection." (PMID 28511718, 2017). "Studies to validate this relationship, identify the source of IL-18, and determine whether it is cause, consequence, or epiphenomenon of myocardial pathology are needed to extend our mechanistic understanding of recovery from SARS-CoV-2 and other viral infections." (PMID 39969260, 2025). "Many reports have focused on IL-12 and IL-18 to identify the TCR-independent activation programs of MAIT cells, or in the context of bacterial and viral infections." (PMID 40519914, 2025). "The early induction of Th1 cytokines such as IL-1β and IL-18 is protective to infected hosts by promoting CD8+ T-cell activity and antibody responses, and IL-27 is effective against viral infections by decreasing immunopathology and increasing survival." (PMID 39066362, 2024). "During viral infection, a complex cascade involving NLRP3, ASC and Pro-caspase-1 forms to process the precursors of IL-1β and IL-18 into active forms." (PMID 39038050, 2024). "Both HIF-1α knockdown and treating the myocardial cell with QFPDD significantly reversed the increased inflammatory factors (IFN-β, IL-18, and TNF-α) mediated by viral infection." (PMID 38476329, 2024). "Taken together, our results show that PVM and MCMV viral infection results in thymic atrophy, accompanied by increased availability of TL1A and IL-18 and alterations in the thymic neutrophil compartment." (PMID 38839915, 2024). "Along with the link between surface receptor expression and downstream intracellular signaling, this study explicated the reduction of CD16 via an IL-18/ADAM17-driven mechanism in HIV-1/SIV infection, as seen in other viral infections." (PMID 37669308, 2023).
viral infection (continued). "The mRNA expression levels of IL-6, IL-18, IFN-α, IFN-β, and ISG-15 in the peripheral blood mononuclear cells (PBMCs) were significantly up-regulated during viral infection." (PMID 37632087, 2023). "Production of IL-18 and interferon (IFN)-γ for fighting cytoplasmic viral infections was dependent on AIM2 activation during mCMV infection in mice." (PMID 36298668, 2022). "In viral infections, MAIT cells can be activated in a TCR-independent manner through inflammatory cytokines such as IL-12, IL-18, and IL-1537,64,65." (PMID 35546552, 2022). "In contrast, significant induction of IL-1β and IL-18, was only observed in THP1/PMA CD169+ macrophages and primary MDMs, suggesting that CD169-mediated viral infection uncouples induction of inflammatory responses from robust viral replication." (PMID 36279285, 2022). "Although MAIT cells cannot detect viral antigen, it has been shown that MAIT cells are activated in viral infections in a TCR-independent manner requiring signalling through IL-12 and IL-18." (PMID 33546489, 2021). "Activation of MAIT cells in viral infections is mediated by T cell receptor (TCR)-independent activation by IL-12 and IL-18." (PMID 33546489, 2021). "Cytokines, such as IL-12, IL-18, and type I IFN, released by APCs upon bacterial or viral infection can also activate MAIT cells in a MR1-independent manner." (PMID 32788367, 2020). "During a typical viral infection, pro-inflammatory cytokines, such as Type 1 IFN, IL-12, IL-15, and IL-18, are generally elevated, inducing NK cell blastogenesis in early virus infection." (PMID 33365027, 2020). "We propose that in response to viral infection, mtROS is produced by damaged and depolarized mitochondria leading to NLRP3 activation and antiviral inflammation that is driven by IL-1β and IL-18." (PMID 31229895, 2019). "In the process of virus infection and lung damage, the NLRP3 inflammasome pathway is very critical and is closely bound up with IL-1β, IL-33, and IL-18." (PMID 32047436, 2019). "Meanwhile, B4GALT5 up-regulated the expression of IFN-α and inflammatory factors (IL6, IL-18, IL-1β, TNF-α) to resist viral infection." (PMID 29546034, 2018). "The IL-12– and IL-18–mediated activation of MAIT cells is likely to have desired consequences during, for example, a local virus infection, in which enhanced IFNγ production can help limit virus replication." (PMID 28742082, 2017). "Corresponding to activation of MAIT cells in viral infection, previous studies showed that TLR8 and TLR3 are potent activators of MAIT cells, promoting the secretion of IL-12 and IL-18 by APCs." (PMID 29176983, 2017). "The circulating levels of IL-18 are remarkably high in both MAS and viral infections, even in comparison to severe bacterial sepsis." (PMID 27977798, 2016). "Thus we are confident that bacterial and viral infections cause the release of EVs into the airway, and if there are high levels of ATP present in the airway (like in asthma and COPD), it could trigger the release of IL-1β and IL-18." (PMID 24972036, 2014). "Sendai virus and influenza A virus were the earliest viruses to be studied for their ability to activate caspase-1 through NLRP3, thereby promoting the production of IL-1β and IL-18, which provided evidence for the involvement of the NLRP3 inflammasome in the viral infection response." (PMID 40906404, 2025). "In our study, the transcription levels of TNF-α, IL-18, IFN-α, and IFN-λ3 were reduced in the early stage of virus infection (within 6 dpi), the transcription levels increased gradually but were maintained at a level equivalent to that of the control group from dpi 12 onward." (PMID 41293456, 2025). "Furthermore, alveolar macrophages highly express IL-18, which is of importance for the development of lung CD103+CD8+ resident memory T cells during viral infections." (PMID 36992195, 2023).